DRC8 (dynein regulatory complex subunit 8)
Description:
Component of the nexin-dynein regulatory complex (N-DRC), a key regulator of ciliary/flagellar motility which maintains the alignment and integrity of the distal axoneme and regulates microtubule sliding in motile axonemes.
Synonyms: EFCAB2; MGC12458; CFAP200
Tractability: Small molecule: a structure with a bound ligand is known. Antibody: the Human Protein Atlas places it where antibodies can reach. PROTAC: ubiquitination databases record sites on it.
Gene: Protein-coding gene on chromosome 1 (244,969,682 to 245,127,164, forward strand). Ensembl gene ENSG00000203666.
Subcellular location: Cytoplasm, cytoskeleton, flagellum axoneme
Subcellular location (Human Protein Atlas): Cytosol; Mid piece; Plasma membrane; Mitochondria
Gene Ontology:
Molecular function: calcium ion binding
Biological process: cilium movement; flagellated sperm motility
Cellular component: axonemal nexin link; axoneme; sperm principal piece; organelle
Genetic constraint (gnomAD): Loss-of-function variants: 24 observed, 23.01 expected, observed/expected ratio (o/e) 1.04, 90% interval 0.75 to 1.47. The upper end of that interval is the gene's LOEUF score, 1.47, which puts it in group 6 of 6, group 1 being the genes least tolerant of losing a copy. Missense variants: 191 observed, 186.89 expected, observed/expected ratio (o/e) 1.02, 90% interval 0.91 to 1.15. Synonymous variants: 52 observed, 52.62 expected, observed/expected ratio (o/e) 0.99, 90% interval 0.79 to 1.25.
Homologues: Orthologues: macaque EFCAB2 (99% identical), mouse Efcab2 (86% identical), guinea pig EFCAB2 (83% identical), rabbit EFCAB2 (82% identical), pig EFCAB2 (78% identical), tropical clawed frog efcab2 (74% identical), chimpanzee EFCAB2 (73% identical), rat Efcab2 (72% identical), dog EFCAB2 (60% identical), Drosophila melanogaster CG9406 (38% identical), Caenorhabditis elegans cal-1 (30% identical), Caenorhabditis elegans cal-3 (27% identical), and 4 more. Paralogues in human: CALM1 (33% identical), CALM2 (33% identical), CALM3 (33% identical), CALML3 (32% identical), CETN1 (30% identical), CETN2 (30% identical), CALML6 (28% identical), CETN3 (28% identical), CALML5 (27% identical), CABP2 (27% identical), CABP4 (26% identical), CABP7 (25% identical), and 8 more.
Diseases named in the same sentence as DRC8 in open-access papers:
DRC8 is named in the same sentence as 3 diseases in open-access papers, as found by Europe PMC text mining. Sharing a sentence is not in itself a finding about the gene and the disease.
DRC8 shares sentences with these, for which no sentence is quoted: breast carcinoma (1 paper); lung carcinoma (1); meningioma (1).